PINX1 (PIN2 (TERF1) interacting telomerase inhibitor 1)
Diseases named in the same sentence as PINX1 in open-access papers (continued):
Sharing a sentence is not in itself a finding about the gene and the disease.
lymph node metastasis (5 papers, 2014 to 2018). "Nine, 11, 12, 11, 10, and 5 studies reported associations between PINX1 expression and sex, depth of invasion, lymph node metastasis, tumor differentiation, tumor-node-metastasis (TNM) stage, and distant metastasis, respectively." (PMID 30079348, 2018). "The results of the pooled analysis showed that low PINX1 expression was associated with lymph node metastasis (OR: 2.23, 95.0% CI: 1.35–3.70; P = 0.002) and advanced TNM stage (OR: 2.43, 95.0% CI: 1.29–4.57; P = 0.006)." (PMID 30079348, 2018). "With respect to the clinicopathological characteristics, we showed that low PINX1 expression was associated with lymph node metastasis and advanced TNM stage." (PMID 30079348, 2018). "We found that low PinX1 expression was associated with lymph node metastasis (P = 0.002) and histology grade (P = 0.001) in patients, as well as with poorer overall and disease-specific survival (P = 0.010 and P = 0.003, respectively)." (PMID 25888829, 2015). "Our data showed that low PinX1 expression was associated with lymph node metastasis and histology grade in patients, as well as with poorer overall and disease-specific survival." (PMID 25888829, 2015). "We also found that PinX1 expression is significantly correlated with lymph node metastasis (P = 0.002, χ2 test)." (PMID 25888829, 2015). "Low PinX1 expression was significantly correlated with depth of invasion, lymph node metastasis and advanced TNM stage in patients, as well as with worse overall and disease-specific survival." (PMID 26033551, 2015). "Reduced expression of PinX1 in patients was correlated with advanced clinical stage (χ2 = 10.230, p = 0.017), high Gleason score (χ2 = 4.019, p = 0.045), positive regional lymph node metastasis (χ2 = 10.852, p = 0.004) and distant metastasis (χ2 = 7.965, p = 0.005)." (PMID 24936151, 2014).
non-small cell lung carcinoma (5 papers, 2017 to 2024). A group of at least three distinct histological types of lung cancer, including non-small cell squamous cell carcinoma, adenocarcinoma, and large cell carcinoma. "We aimed to investigate the effects of PinX1 on non-small cell lung cancer(NSCLC) radiosensitivity and radiotherapy-associated tumor immune microenvironment and its mechanisms." (PMID 38431575, 2024). "For instance, PinX1 expression has recently been proposed as a prognostic factor for human non-small cell lung cancer." (PMID 31210926, 2019). "However, the clinical and biological significance of PinX1 in human non-small cell lung cancer (NSCLC) is unclear." (PMID 28372542, 2017). "PinX1 expression status and its correlation with clinicopathological features in non-small-cell lung cancer (NSCLC) have not been investigated." (PMID 28815183, 2017).
cervical squamous cell carcinoma (4 papers, 2016 to 2025). A squamous cell carcinoma arising from the cervical epithelium. "First, only a single study reported the prognostic value of PINX1 expression in each of the following: cervical squamous cell carcinoma, esophageal squamous cell carcinoma, and glioma, respectively." (PMID 30079348, 2018). "In cervical squamous cell carcinoma and endocervical adenocarcinoma (CESC), which is featured by short telomeres and high telomerase activity, PinX1-TID efficiently inhibits cancer stemness traits by primarily targeting telomerase activity." (PMID 39634130, 2025). "However, among the 14 studies included in this meta-analysis, 3 reported on cervical squamous cell carcinoma, esophageal squamous cell carcinoma, and glioma where PINX1 expression has been reported to have an opposite prognostic effect compared to the pooled outcome." (PMID 30079348, 2018). "Interestingly, knockdown of PinX1 dramatically enhanced paclitaxel cytotoxicity to cervical squamous cell carcinomas cells and knockdown of PinX1 substantially increased ESCC (oesophageal squamous cell carcinoma) cells' therapeutic efficacy of radiation both in vitro and in vivo." (PMID 27556185, 2016).
esophageal squamous cell carcinoma (4 papers, 2016 to 2024). Esophageal squamous cell carcinoma (ESCC) is a type of esophageal carcinoma (EC) that can affect any part of the esophagus, but is usually located in the upper or middle third. "For example, one study demonstrated that high expression of PinX1 in esophageal squamous cell carcinoma is associated with a patient’s chemoradiotherapy resistance and can predict his/her survival." (PMID 28978030, 2017). "Additionally, we found PIN2/TERF1-interacting telomerase inhibitor (PinX1), a telomerase binding factor, induces radioresistance through improved telomere stability in esophageal squamous cell carcinoma(ESCC)." (PMID 38431575, 2024). "Moreover, the relationship between PINX1 expression and response to chemoradiotherapy was considered a clinical parameter in cervical and esophageal squamous cell carcinomas, the mechanism of which has not been determined." (PMID 30079348, 2018).
glioma (4 papers, 2014 to 2022). A benign or malignant brain and spinal cord tumor that arises from glial cells (astrocytes, oligodendrocytes, ependymal cells). "In contrast, there is evidence that PINX1 expression is associated with poor survival in glioma patients because it promotes cell proliferation." (PMID 36142793, 2022). "In the present study, PinX1 was knocked-down in C6 cells and cell viability was analyzed to confirm the potential of PinX1 as a target gene for the treatment of gliomas." (PMID 24940406, 2014). "Specific siRNA molecules, delivered by mPEG-PEI-SPION, were employed to knockdown the PIN2-interacting protein 1 (PinX1) gene in C6 glioma cells." (PMID 24940406, 2014). "The aims of the present study were to determine whether mPEG-PEI-SPION may be a device for siRNA delivery into C6 cells and whether the specific silencing of PinX1 by siRNA may improve the cytotoxic effect of DOX in C6 glioma cells." (PMID 24940406, 2014). "Furthermore, gliomas were treated with a combination of PinX1-siRNA and DOX, with the aim of increasing the efficiency of the treatment and decreasing the side effects." (PMID 24940406, 2014). "Therefore, mPEG-PEI-SPION was shown to be viable for siRNA delivery into C6 cells and coadministration of DOX with PinX1-siRNA may be a potential therapeutic method for inhibiting gliomas." (PMID 24940406, 2014). "Of the eight investigated genes involved in telomere maintenance and telomerase regulation, three (PINX1, TNKS, and TNKS2) were found to be downregulated in all glioma cell lines when compared to individual controls." (PMID 36142793, 2022).
hepatocellular carcinoma (4 papers, 2014 to 2025). A malignant tumor that arises from hepatocytes. "Moreover, PinX1 overexpression significantly suppresses the growth of hepatocellular carcinoma cells, whereas PinX1 inhibition potently enhances cell growth." (PMID 27556185, 2016).
liver cancer (4 papers, 2011 to 2025). An epithelial or non-epithelial malignant neoplasm that arises from the liver. "This region is also a common integration site for hepatitis B virus, a well-known major risk factor in liver cancer and PinX1 is reduced in ~ 40% hepatitis B virus-related liver cancer." (PMID 22021332, 2011).
nasopharyngeal carcinoma (4 papers, 2012 to 2025). A carcinoma arising from the nasopharyngeal epithelium. "Here we show that PinX1 is essential for down-regulation telomerase activity of nasopharyngeal carcinoma." (PMID 22316341, 2012).
atherosclerosis (3 papers, 2017 to 2021). A disease characterized by the build-up of fatty material and calcium deposition in the arterial wall resulting in partial or complete occlusion of the arterial lumen. "A relevant study showed that the PINX1 mutations increased the risk of carotid intima media thickness, which is used to determine atherosclerosis, a chronic formation process caused by excessive cholesterol deposition in the arterial intima." (PMID 29371971, 2017). "TRIP6, PINX1, and ERI1 have notably been associated with blood pressure, triglyceride levels, HDL cholesterol, diabetes mellitus, and atherosclerosis." (PMID 34753499, 2021). "The gene-based association identified genes (TRIP6, PINX1 and ERI1) were significantly associated with expression change in the whole blood and lung and have previously been associated with blood pressure, triglyceride levels, HDL cholesterol, diabetes mellitus and atherosclerosis." (PMID 34753499, 2021).
colon cancer (3 papers, 2012 to 2025). "We found that PinX1 was elevated in most colon cancer cells compared with NCM460 cells." (PMID 40639785, 2025).
bladder cancer (2 papers, 2012 to 2017). "All of the SNPs in TEP1 were associated with increased risk, and all SNPs except one in PINX1 were associated with reduced risk of bladder cancer." (PMID 22363464, 2012). "In addition to TEP1, we found high significance in a SNP on the PINX1 gene and lower bladder cancer risk." (PMID 22363464, 2012).
bladder urothelial carcinoma (2 papers, 2013 to 2017). "With the exception of the high frequency of PinX1 gene deletion, we also found that PinX1 genetic mutations occurred in some types of human cancers, including bladder urothelial carcinoma, lung adenocarcinoma, and melanoma." (PMID 28978030, 2017). "However, another study showed that PinX1 expression in bladder urothelial carcinoma was significantly down-regulated at both the mRNA and protein levels when compared with normal tissue." (PMID 28978030, 2017). "However, the possible involvement of PinX1 and its clinical/prognostic significance in urothelial carcinoma of the bladder (UCB) are unclear." (PMID 24268029, 2013). "Our results demonstrated that PinX1 gene alterations were correlated with poor survival in patients with lung adenocarcinoma (overall survival and disease-free survival) and as well as those diagnosed with bladder urothelial carcinoma (disease-free survival only)." (PMID 28978030, 2017).
cervical cancer (2 papers, 2015 to 2017). A primary or metastatic malignant neoplasm involving the cervix.
injury (2 papers, 2021 to 2022). Damage inflicted on the body as the direct or indirect result of an external force, with or without disruption of structural continuity. "However, PINX1-uregulation exhibited the highest expression of NF-κB p65 in lung tissues of LPS-induced lung injury rats." (PMID 33819185, 2021).
lentivirus infection (2 papers, 2015). Virus diseases caused by the Lentivirus genus. "After 3 weeks selection following with lentivirus infection, the PinX1 protein levels of these cell lines were confirmed by western blot." (PMID 25888829, 2015).
lung adenocarcinoma (2 papers, 2017). A carcinoma that arises from the lung and is characterized by the presence of malignant glandular epithelial cells. "There were more PinX1 homozygous deletions and PinX1 heterozygous deficiencies and less PinX1 amplifications in two specific NSCLC datasets (namely Lung Squamous Carcinoma – TCGA, Provisional and Lung Adenocarcinoma –TCGA, Provisional)." (PMID 28372542, 2017). "In addition, the frequency of PinX1 gene deletion in adenocarcinoma was more than squamous carcinoma in some solid tumors, such as 6.1% (TCGA, Nature), 5.5% (Broad, Cell), and 5.7% (TCGA, Provisional) in lung adenocarcinoma versus 1.7% (TCGA, Provisional) in lung squamous cell carcinoma." (PMID 28978030, 2017). "The deletion of PinX1 gene accounted for the most alterations and was visualized in six NSCLC database (Lung Adenocarcinoma – Broad, Cell 2012; TCGA, Provisional; TCGA, Nature 2014; TSP, Nature 2008; Lung Squamous Carcinoma – TCGA, Provisional; TCGA, Nature 2012)." (PMID 28372542, 2017).
melanoma (2 papers, 2017). A malignant, usually aggressive tumor composed of atypical, neoplastic melanocytes. "We reported increasing nucleolin expression with melanoma progression, which does not readily explain the trend for TERT; however we know of no data on PINX1 expression in melanoma." (PMID 29262649, 2017).
Obesity (2 papers, 2021 to 2022). Accumulation of substantial excess body fat. "It is worth noting that UTP14A, DKC1, and PinX1 are all closely associated with angiogenesis in various diseases, so we speculate that all three may affect cardiac angiogenesis in obesity, but their angiogenic roles in cardiac tissue remain unclear." (PMID 35734237, 2022). "In this study, UTP14A and PinX1 were identified as key genes in the heart of obese mice, which may be involved in the pathophysiology of obesity-related cardiac effects by regulating the balance of cardiac microvasculature, but there is no relevant research to verify this." (PMID 35734237, 2022). "UTP14A, DKC1, DDX10, PinX1, and ESF1 may be involved in obesity-induced cardiac injury by affecting angiogenesis in the heart." (PMID 35734237, 2022). "UTP14A, DKC1, DDX10, PinX1, and ESF1 have been identified as hub genes in obesity-induced pathological changes in the heart and may be involved in obesity-induced cardiac injury by affecting cardiac microcirculatory function." (PMID 35734237, 2022).
prostate adenocarcinoma (2 papers, 2014 to 2017). "The subcellular localization and expression of the PinX1 protein were observed and scored by IHC on the TMA, which including 40 prostate adenocarcinoma and 8 normal prostate tissues." (PMID 24936151, 2014).
Alzheimer disease (1 paper, 2020). A progressive, neurodegenerative disease characterized by loss of function and death of nerve cells in several areas of the brain leading to loss of cognitive function such as memory and language. "Pinx1 is a telomerase inhibitor with little known brain function, although variants have been associated with late-onset Alzheimer disease." (PMID 32174962, 2020).
bladder tumor (1 paper, 2013). "The IHC results demonstrated that negative expression of PinX1 protein in 44.4% of primary bladder tumor, but in only 20.6% of normal bladder epithelial tissues." (PMID 24268029, 2013).
carcinosarcoma (1 paper, 2017). A malignant tumor composed of a mixture of carcinomatous and sarcomatous elements. "Our results showed that PinX1 deletion accounted for the most alterations, with the frequency of its deletion regularly occurring in pathological types of carcinosarcoma and adenocarcinoma." (PMID 28978030, 2017). "In addition, we also observed that the genotype of PinX1 gene deletion often occurred in both carcinosarcoma and adenocarcinoma." (PMID 28978030, 2017). "Furthermore, the frequency of PinX1 deletion often occurred in the two specific pathological types of carcinosarcoma and adenocarcinoma." (PMID 28978030, 2017).
clear cell renal cell carcinoma (1 paper, 2015). "This study explored the clinical significance and biological function of PinX1 in human clear cell renal cell carcinoma (ccRCC)." (PMID 26033551, 2015). "Immunohistochemistry staining was utilized in TMA slides to evaluate the PinX1 expression in normal renal tissues, clear cell renal cell carcinoma tissues and paired adjacent non-tumor tissues." (PMID 26033551, 2015). "Moreover, univariate and multivariate Cox proportional hazards regression analysis investigated that low PinX1 expression was a strong independent negative prognostic indicator for clear cell renal cell carcinoma." (PMID 26033551, 2015).
colon adenocarcinoma (1 paper, 2025). "To investigate the role of PinX1 in cancers, we examined the expression levels of PinX1 in The Cancer Genome Atlas (TCGA) and GTEx database and found PinX1 was elevated both in colon adenocarcinoma (COAD) and rectum adenocarcinoma (READ) compared with the normal tissues." (PMID 40639785, 2025).
glioblastoma (1 paper, 2022). The most malignant astrocytic tumor (WHO grade IV). "In glioblastoma cell lines with induced overexpression of PINX1, there was a reduction in cell migration and proliferation due to cell cycle arrest at the G1 phase." (PMID 36142793, 2022).
osteosarcoma (1 paper, 2019). A usually aggressive malignant bone-forming mesenchymal neoplasm, predominantly affecting adolescents and young adults. "PinX1 involvement in a telomerase-independent mechanism that led to telomere dysfunction had been suggested in osteosarcoma cells." (PMID 31210926, 2019).
renal carcinoma (1 paper, 2024). A carcinoma arising from the epithelium of the renal parenchyma or the renal pelvis. "A recent study reported that PinX1 inhibited renal cancer angiogenesis via the VEGF signaling pathway." (PMID 39469202, 2024).
schizophrenia (1 paper, 2019). A major psychotic disorder characterized by abnormalities in the perception or expression of reality. "Several other genes in this region show suggestive evidence of differential expression/splicing in ASD, including MSRA, which has been previously associated with schizophrenia, MFHAS1, and PINX1." (PMID 31230729, 2019).
scleroderma (1 paper, 2021). Scleroderma is a rare autoimmune connective tissue disorder characterized by abnormal hardening of the skin and, sometimes, other organs. "PINX1 has been reported to be associated with systemic sclerosis (SSc (scleroderma)) in both African-American and White populations." (PMID 34337078, 2021).